MGMT (O-6-methylguanine-DNA methyltransferase)
Diseases named in the same sentence as MGMT in open-access papers (continued):
Sharing a sentence is not in itself a finding about the gene and the disease.
tumor (continued). "MGMT removes alkyl groups from guanine in the DNA, potentially counteracting the therapeutic efficacy of alkylating chemotherapeutics, such as TMZ, in tumor cells." (PMID 31766430, 2019). "Analysis of MGMT methylation by MSP-tumor was informative for all 73 patients, while analysis by PYR-tumor was informative for all 74 patients." (PMID 31366977, 2019). "Together, these studies uncover a mechanism that regulates MGMT expression, confers TMZ resistance, and potentially regulates tumor proliferation." (PMID 30054476, 2018). "The list of genes with stringently tumor-specific hypermethylation includes, for instance, ERCC1, MGMT, POLD1, and RBBP8/CtiP." (PMID 29445424, 2018). "We next analyzed the putative correlation between the TMZ/miR-370-induced reduction in tumor volume and the TMZ/miR-370-induced reduction in MGMT expression." (PMID 30497054, 2018). "MGMT-unmethylated tumors have a higher percentage of tumor enhancement and T2/FLAIR hyperintensity when compared to MGMT-methylated tumors." (PMID 29581794, 2018). "Methylation of the MGMT promoter occurs in approximately 45% of GBM patients, and it has become a reliable prognostic indicator of TMZ therapy in this type of tumor." (PMID 29963012, 2018). "We observed epigenetic silencing of important tumor suppressors, including BRCA1, MGMT, and RASSF1A exclusively in NSGCTs." (PMID 29898407, 2018). "Here we report that an enhancer, located between the promoters of marker of proliferation Ki67 (MKI67) and O6-methylguanine-DNA-methyltransferase (MGMT) genes, is activated in TMZ-resistant patient-derived xenograft (PDX) lines and recurrent tumor samples." (PMID 30054476, 2018). "Through its MGMT targeting arm, it can induce S-benzylation and down-regulation of MGMT and potentiation of TMZ in tumour cells co-expressing EGFR and MGMT." (PMID 30416678, 2018). "Aberrant methylation of three genes (BRCA1, MGMT, and MLH1), playing important roles in the different DNA repair mechanisms, were dependent on the tumor subtype and represent powerful biomarkers for precision therapy." (PMID 29882921, 2018). "This was evidenced by a decreased level of the following parameters: a proliferation marker (Ki-67), a tumor growth marker (18F-fluorothymidine uptake, determined by PET/CT images), and the MGMT enzyme." (PMID 30583528, 2018). "Meanwhile, western blot analysis revealed that xenograft tumor treated by TMZ showed increased expression of TGF-β1/CTGF signal axis and higher expression of MDR phenotype (MDR1, MRP1, BCRP) and MGMT on day 35 as compared to the PBS Control group." (PMID 28617438, 2017). "The results showed that in tumor tissues, miR-29c expression was down-regulated while SP1 and MGMT mRNA expression was up-regulated as compared with in PTBE tissues." (PMID 28831025, 2017). "Several of these genes (including MGMT, RAD17, and USP44) show prior evidence of a tumour suppressive function." (PMID 29089486, 2017). "To summary, these findings indicate that lower MGMT expression may be used to predict the recurrence of PAs, however, MGMT expression is not related to other clinicopathological indicators, such as invasiveness age, gender, tumor size, or functional status of patients with PAs." (PMID 28152515, 2017). "Patients of group A and group B were homogeneous for the clinical and molecular features that hold prognostic value, such as age, extent of tumor resection, KPS, and MGMT methylation." (PMID 28248456, 2017). "Using two different assays combined with quantitative image analysis excluding non-tumour cells, APNG was an independent prognostic factor among patients with a methylated MGMT promoter." (PMID 28662073, 2017).
tumor (continued). "An altered methylation pattern of APC, CDH13, MGMT, MLH1 and RUNX3 genes is a well recognized characteristic of CRC tumor cells." (PMID 26862732, 2016). "The methylation statuses of the promoters of 11 tumor-related genes (p16, RASSF1A, E-cadherin, H-cadherin, MGMT, DAPK, DCC, COL1A2, TAC1, SST, and GALR1) were analyzed in 133 HNSCC cases using quantitative methylation-specific PCR." (PMID 27027429, 2016). "Their in vitro study also proved an enhancement of fluorouracil anti-tumor effect for CRC and other malignancies with MGMT methylation by controlling the levels of MGMT in tumor." (PMID 27643594, 2016). "The meta-analysis of p14, p15, p73, APC, SOCS1, MGMT, SFRP1, PRDM2, DAPK1, RARβ, IGF2 and hMLH1 genes methylation was performed between HCC tumor tissues vs adjacent tissues and HCC tumor tissues vs normal tissues." (PMID 27835605, 2016). "Promoter methylation of four candidate tumor suppressor genes (adenylate cyclase 8 (ADCY8), cadherin 8, type 2 (CDH8), MGMT, and zinc finger protein 582 (ZNF582)) out of 48 genes screened was quantified by bisulfite-pyrosequencing of genomic DNA." (PMID 27651839, 2016). "Downregulated factors such as MGMT, p16Ink4A, p27Kip1, Bcl-2, Bax, Bcl-x, and MT3 are involved in the cell cycle, apoptosis, tumor suppression, metabolism, and enhanced TMZ sensitivity." (PMID 27893664, 2016). "Patients were divided into two groups, defined by age, tumor localization, gender, KPS and MGMT promoter methylation status, and a log-rank survival analysis was performed." (PMID 27108407, 2016). "A multivariate Cox regression model incorporating age, gender, cohort, KPS, tumor location, surgical history, TERT, and MGMT revealed that the interaction between TERT and MGMT was significant for OS in the combined GBM cohort of 453 cases." (PMID 27503138, 2016). "Analysis of 17 metachronous paired tumors showed frequent biomarker changes, including MGMT-methylation and EGFR aberrations, indicating the need for a re-biopsy for tumor profiling to direct subsequent therapy." (PMID 26933808, 2016). "Using the methylation PCR array, we have demonstrated that overexpression of ERp29 resulted in hypomethylation of CpG islands in tumour suppressor genes such as CDH1, p16 and MGMT, thereby leading to upregulation of these genes." (PMID 26420420, 2015). "In the present study, 171 miRNAs were found to be differentially expressed between non-tumor brain tissue and GBM specimens with MGMT promoter methylation." (PMID 26320189, 2015). "In only 59 % (10/17), 53 % (9/17), 41 % (7/17), 38 % (6/16) and 35 % (6/17) of the tumor samples, RASSF1A, HIN-1, MGMT, DAPK1 and CCND2 promoters showed methylation status ≥ LOQ." (PMID 26370119, 2015). "To determine the relationship between MGMT promoter gene methylation, MGMT expression, and TMZ treatment, we analyzed the methylation status of the promoter in all tumor cell lines before and after TMZ treatment." (PMID 26447477, 2015). "Here we present a microfluidic chip to analyse mRNA levels of MGMT and APNG in enriched tumour exosomes obtained from blood." (PMID 25959588, 2015). "The aim of this study was to analyze the relevance of MGMT, the MMR system and P-gp in the development of resistance against TMZ in tumor cell lines A172, LN229, SF268 and SK-N-SH." (PMID 26447477, 2015). "In tumor-adjacent and tumor-distant tissues, the RASSF1A promoter was as frequently and the HIN-1, MGMT and GSTP1 promoters were almost as frequently methylated as in tumors." (PMID 26370119, 2015). "Our results showed two clearly differentiated groups of tumor cells characterized by low (A172 and LN229) and high (SF268 and SK-N-SH) basal MGMT expression." (PMID 26447477, 2015).
tumor (continued). "The data presented in adult tumours provide compelling evidence for the role of APE1, NBN, PMS2, MGMT and PTEN in gliomagenesis." (PMID 25026297, 2014). "It is widely accepted that hypermethylation of the promoter of the MGMT gene in the tumor tissue can predict sensitivity to TMZ, since hypermethylation prevents the expression of MGMT thereby sensitizing the cells to TMZ." (PMID 24495907, 2014). "The expression pattern of the two molecules and MGMT methylation status were correlated with overall survival (OS), disease-free survival (DFS), tumor stage, and differentiation grade, among others." (PMID 25015560, 2014). "All of these genes are known to be involved in different aspects of breast carcinogenesis, which includes tumor suppression, HIC1, CDH1, CDH13, CDKN2, DNA repair, MGMT, apoptosis, PYCARD, TNFRSF10C, and cell cycle regulation, CCNA1." (PMID 25403427, 2014). "In these cancers, the methylation of the promoter regions of tumor suppressor genes, such as CDH1, APC, MGMT, RASSF1A, GSTP1, p16 and RAR-β2, affect the activity of tumor suppressor genes, typically leading to transcriptional silencing." (PMID 24748968, 2014). "Subsequent studies provided evidence that TMZ and radiotherapy act synergistically to promote tumor killing through TMZ-mediated radiation enhancement, specifically in those GBMs that have undetectable MGMT expression." (PMID 25268164, 2014). "The data presented above provides evidence that APE1, NBN, PMS2, MGMT and PTEN mRNA expression levels have prognostic and predictive significance in adult tumours." (PMID 25026297, 2014). "The relevance of MGMT in CRC carcinogenesis is widely accepted, and reduced MGMT expression has been documented in tumor versus normal colon tissue; however, the mechanism by which MGMT expression is controlled remains controversial." (PMID 25015560, 2014). "Immunofluorescent staining of patient tumour specimens revealed a 51 ± 9% overlap between ZEB1 and MGMT, which corroborated the significant correlation between ZEB1 and MGMT indicated by Western analysis (arrowheads)." (PMID 23818228, 2013). "It suggested that MGMT gene promoter methylation was a frequent event in NSCLC, but it rarely happened in the non-tumor group." (PMID 24086261, 2013). "Despite the complex interpretation of MSI, we conclude that both the MGMT and MMR pathways play major roles in the tumor response to TMZ treatment." (PMID 24287492, 2013). "In our own current practice, we carry out double-labelling for MGMT and "cocktail" (CD34, CD45 and CD68) to come to an initial conclusion as to the likely methylation status of the tumour." (PMID 24252243, 2013). "In GBM, there is frequent hypermethylation of tumour suppressors (RB1, EMP3, RASSF1A and BLU), cell cycle regulators (p16INK4a and p15INK4b), DNA repair genes (MGMT, MLH1), and genes involved in tumour invasion and apoptosis (DAPK, TIMP3 and CDH1)." (PMID 22771539, 2013). "Two approaches are currently being taken to develop new TMZ derivatives that are resistant to, or avoid, the two principal constraints on the ability of a tumor to respond to TMZ therapy, viz, MGMT and MMR dependence." (PMID 24287492, 2013). "However, association of tumor grade with methylated MGMT gene was not statistically significant." (PMID 23573237, 2013). "Because tumor cells that express MGMT are more resistant to TMZ, targeting the MGMT activity can enhance the therapeutic efficiency of TMZ." (PMID 22912934, 2012). "A total of 15 genes (AIM1, ARF, CCNA1, MGMT, hMLH1, PGP9.5, S100A2, APC, RAR-β2, ER-α, ER-β, MCAM, VGF, FKBP4 and SSBP2) were analysed for promoter methylation using QMSP in 57 tumour samples, comprising 43 SEs and 14 NSEs, and 23 NT samples." (PMID 22068818, 2012).
tumor (continued). "5-Aza application resulted in partial demethylation of the MGMT and RASSF1A TSGs and reduced proliferation of the tumor cells suggesting further evaluation of 5-Aza for HNSCC treatment." (PMID 22246327, 2012). "Known tumor suppressor genes, e.g., CDKN2A (9p21.3), PTEN (10q23), and RB1 (13q14) were located within HD regions, as well as genes with potential tumor suppressor properties, e.g., CUL3 (2q36.2) and MGMT (10q26)." (PMID 22685613, 2012). "Finally, methylation is not biallelic in some tumours, leaving one allele actively expressing the protein while MGMT promoter methylation may be also observed." (PMID 21269507, 2011). "We have previously shown that PARP inhibitors can restore temozolomide sensitivity to MMR-defective cells, and sensitise tumour cells and xenografts, including models competent for MMR and MGMT, to temozolomide." (PMID 20978505, 2010). "DNA methylation at the promoter region of the MGMT, CDKN2A, SFRP1, TMEFF2, HS3ST2 (3OST2), RASSF1A and GATA4 genes was evaluated by quantitative methylation specific PCR in both tumor and corresponding normal appearing colorectal mucosa samples." (PMID 20098741, 2010). "Classical tumour suppressor genes and genes involved in chemosensitivity, such as hMLH1, p16, p15, Rb, VHL, E-cadherin, GSTP1, and BRCA1, or the DNA repair gene MGMT, undergo epigenetic inactivation by hypermethylation of their regulatory regions." (PMID 19144202, 2009). "In common with other cancers, WTs also show tumour suppressor gene silencing which includes genes such as HACE1 (73% of tumours analysed), RASSF1 (56%), CASP8 (43%), MGMT (30%), RASSF5/NORE1 (15%), and CDKN2A (10–15%)." (PMID 19956686, 2009). "Three markers – DIRAS3, MGMT, and HRAS – showed statistically significant hypermethylation in non-tumor tissue." (PMID 18616821, 2008). "A recent study reported promoter methylation profiles of hMLH1, MGMT and CDKN2A in 51 cases of HNSCCs using MSP and demonstrated that tumours with two or more methylated genes had improved DFS at 2 years." (PMID 18594522, 2008). "However, given the variable levels of expression of MGMT in this tumour type, it would be beneficial to assess MGMT levels in tumour biopsies from all patients in such a study so that the hypothesis that MGMT inactivation will be beneficial can be effectively tested." (PMID 16278661, 2005). "Promoter hypermethylation in 10 tumour-related genes (APC, E-cadherin, GSTP1, hMLH1, MGMT, p15, p16, SOCS1, TIMP3 and TGF-beta RII) was determined by quantitative methylation-specific PCR (MethyLight)." (PMID 15942635, 2005). "Hypermethylation of MGMT (in 14 tumours), CDH1 (in nine tumours), RAR-β (in eight tumours) and SYK (in seven tumours) have been found." (PMID 14970867, 2004). "Several genes including tumour suppressor genes and DNA repair genes such as hMLH1, RB1, VHL, p15, p16, RASSF1A, MGMT and BRCA1 in human cancers were shown to be epigenetically inactivated by DNA methylation in tumours." (PMID 14970867, 2004). "Here, we report the existence of human HCCs lacking both MGMT and hMLH1 proteins, the relation between HCCs associated with hepatitis viral infection and detailed CpG methylation status of MGMT and hMLH1 promoter regions, and the specific CpG methylation pattern of MGMT- and hMLH1-negative tumours." (PMID 12592365, 2003).
tumor (continued). "The contrasting methylation patterns of MGMT/NUPR1 and NDRG2/GLI1 in GBM may shed light on their opposing roles in tumor development and progression." (PMID 41596413, 2026). "CBD sensitized U87and GBM163 intracranial tumors to TMZ and showed a considerable increasein survival in tumor-bearing mice (the effect was absent in orthotopicGBM models with intact MGMT expression)." (PMID 41288593, 2026). "The overarching rationale was to create a multi-faceted epigenetic panel that captures different aspects of GBM biology: DNA repair and chemoresistance (MGMT), stress response and oncogenic signaling (NUPR1), tumor suppression (NDRG2), and developmental pathway activation (GLI1)." (PMID 41596413, 2026). "No group differences were seen in contrast-enhancing tumor volume, T1w subtraction map values, and qT2*, nor in clinical variables such as sex category, MGMT status, and EGFR status." (PMID 40227555, 2025). "Consistent with prior results, tumor grade 2 versus grade 3 and MGMT-methylation were not significant independent prognostic features." (PMID 39164213, 2025). "Among these, MGMT directly counteracts TMZ’s alkylating action by removing methyl adducts from the O6 position of guanine, thereby preventing DNA damage and facilitating tumor survival." (PMID 40429865, 2025). "To assess the impact of TTFields on the procoagulant activity of tumor cells, we quantified surface TF levels and conducted transcriptomic analysis on four patient-derived GBM cell lines: two with unmethylated MGMT promoter status (HROG04, GBM15) and two with methylated MGMT (HROG13, GBM06)." (PMID 40885689, 2025). "MGMT is a DNA-repairing enzyme that counteracts the alkylating effects of TMZ by preventing DNA mismatches and apoptosis, reducing the cytotoxic effect of alkylating agents and resulting in tumor cells resistant to chemotherapy." (PMID 39944537, 2025). "Furthermore, MGMT testing is rarely done in HGG recurrence, despite tumor heterogeneity and potential variance in MGMT methylation." (PMID 41476598, 2025). "Of the IHC negative specimens, only four demonstrated increased MGMT promoter methylation, and one IHC positive tumor showed evidence of hypermethylation by pyrosequencing." (PMID 39825572, 2025). "The ability to predict MGMT status using imaging as opposed to relying on tumor tissue given sample, cost, and timing constraints has been of critical interest in neuro-oncology." (PMID 40428285, 2025). "We recently reported that expression of MGMT in our commonly used GBM cell lines is low as compared to other solid tumor cell lines where it is quite high and that TMZ can have effects on tumor cell killing by T-cells within a few hours before there is time for cell division or mutations to occur." (PMID 40145650, 2025). "In contrast to MLH1 and MGMT expression, the p16INK4a expression was consistently low in control and non-cancerous mucosa, as well as in tumor tissue." (PMID 40357388, 2025). "Tumor MGMT promoter methylation was present in 7 tumors, absent in 9, and indeterminate for 1 patient." (PMID 40595067, 2025). "MGMT RNA expression across 5348 specimens derived from 1056 PDX tumor models in the PDMR shows a bimodal expression profile with ~ 10% of the samples across several different tumor types having no detectable MGMT mRNA." (PMID 40458731, 2025). "Key molecular biomarkers including isocitrate dehydrogenase (IDH) mutation, 1p/19q chromosomal co-deletion, O6-methylguanine-DNA methyltransferase (MGMT) promoter methylation, and WHO tumor grade significantly influence clinical outcomes and treatment response." (PMID 41293309, 2025). "Significant differences in tumor type between the MGMT-methylated and non-methylated groups were observed (p = 0.02)." (PMID 41476598, 2025). "As a consequence, patients with tumours that overexpress MGMT receive little to no benefit from TMZ therapy." (PMID 40377133, 2025).